OR6C68 (olfactory receptor family 6 subfamily C member 68)
Description:
Odorant receptor.
Tractability: Antibody: UniProt places it where antibodies can reach, with medium confidence; UniProt predicts a signal peptide or a membrane-spanning region; its Gene Ontology location is reachable by antibodies, with medium confidence.
Gene: Protein-coding gene on chromosome 12 (55,492,378 to 55,493,316, forward strand). Ensembl gene ENSG00000205327.
Subcellular location: Cell membrane
Pathways (Reactome):
Sensory Perception: Expression and translocation of olfactory receptors
Gene Ontology:
Molecular function: olfactory receptor activity; G protein-coupled receptor activity
Biological process: detection of chemical stimulus involved in sensory perception of smell; G protein-coupled receptor signaling pathway
Cellular component: plasma membrane; membrane
Genetic constraint (gnomAD): Missense variants: 430 observed, 375.81 expected, observed/expected ratio (o/e) 1.14, 90% interval 1.06 to 1.24. Synonymous variants: 154 observed, 134.38 expected, observed/expected ratio (o/e) 1.15, 90% interval 1 to 1.31.
Homologues: Orthologues: chimpanzee OR6C68 (97% identical), mouse Or6c68 (84% identical), rat Or6c68 (82% identical). Paralogues in human: OR6C2 (75% identical), OR6C76 (65% identical), OR6C74 (63% identical), OR6C75 (62% identical), OR6C4 (61% identical), OR6C70 (61% identical), OR6C6 (61% identical), OR6C65 (60% identical), OR6C3 (59% identical), OR2AP1 (58% identical), OR6C1 (58% identical), OR6X1 (43% identical), and 6 more.
Diseases named in the same sentence as OR6C68 in open-access papers:
OR6C68 is named in the same sentence as 1 disease in open-access papers, as found by Europe PMC text mining. Sharing a sentence is not in itself a finding about the gene and the disease.
OR6C68 shares sentences with these, for which no sentence is quoted: cancer (1 paper).